TGFB1 (transforming growth factor beta 1)
Description:
Transforming growth factor beta-1 proprotein: Precursor of the Latency-associated peptide (LAP) and Transforming growth factor beta-1 (TGF-beta-1) chains, which constitute the regulatory and active subunit of TGF-beta-1, respectively. [Latency-associated peptide]: Required to maintain the Transforming growth factor beta-1 (TGF-beta-1) chain in a latent state during storage in extracellular matrix. Associates non-covalently with TGF-beta-1 and regulates its activation via interaction with 'milieu molecules', such as LTBP1, LRRC32/GARP and LRRC33/NRROS, that control activation of TGF-beta-1. Interaction with LRRC33/NRROS regulates activation of TGF-beta-1 in macrophages and microglia (Probable). Interaction with LRRC32/GARP controls activation of TGF-beta-1 on the surface of activated regulatory T-cells (Tregs). Interaction with integrins (ITGAV:ITGB6 or ITGAV:ITGB8) results in distortion of the Latency-associated peptide chain and subsequent release of the active TGF-beta-1. [Transforming growth factor beta-1]: Multifunctional protein that regulates the growth and differentiation of various cell types and is involved in various processes, such as normal development, immune function, microglia function and responses to neurodegeneration (By similarity). Activation into mature form follows different steps: following cleavage of the proprotein in the Golgi apparatus, Latency-associated peptide (LAP) and Transforming growth factor beta-1 (TGF-beta-1) chains remain non-covalently linked rendering TGF-beta-1 inactive during storage in extracellular matrix. At the same time, LAP chain interacts with 'milieu molecules', such as LTBP1, LRRC32/GARP and LRRC33/NRROS that control activation of TGF-beta-1 and maintain it in a latent state during storage in extracellular milieus. TGF-beta-1 is released from LAP by integrins (ITGAV:ITGB6 or ITGAV:ITGB8): integrin-binding to LAP stabilizes an alternative conformation of the LAP bowtie tail and results in distortion of the LAP chain and subsequent release of the active TGF-beta-1. Once activated following release of LAP, TGF-beta-1 acts by binding to TGF-beta receptors (TGFBR1 and TGFBR2), which transduce signal. While expressed by many cells types, TGF-beta-1 only has a very localized range of action within cell environment thanks to fine regulation of its activation by Latency-associated peptide chain (LAP) and 'milieu molecules' (By similarity). Plays an important role in bone remodeling: acts as a potent stimulator of osteoblastic bone formation, causing chemotaxis, proliferation and differentiation in committed osteoblasts (By similarity). Can promote either T-helper 17 cells (Th17) or regulatory T-cells (Treg) lineage differentiation in a concentration-dependent manner (By similarity). At high concentrations, leads to FOXP3-mediated suppression of RORC and down-regulation of IL-17 expression, favoring Treg cell development (By similarity). At low concentrations in concert with IL-6 and IL-21, leads to expression of the IL-17 and IL-23 receptors, favoring differentiation to Th17 cells (By similarity). Stimulates sustained production of collagen through the activation of CREB3L1 by regulated intramembrane proteolysis (RIP). Mediates SMAD2/3 activation by inducing its phosphorylation and subsequent translocation to the nucleus. Positively regulates odontoblastic differentiation in dental papilla cells, via promotion of IPO7-mediated translocation of phosphorylated SMAD2 to the nucleus and subsequent transcription of target genes (By similarity). Can induce epithelial-to-mesenchymal transition (EMT) and cell migration in various cell types.
Synonyms: LAP; TGFB; CED; TGFbeta; CAEND1; DPD1; IBDIMDE; TGF-beta1
Tractability: Small molecule: a structure with a bound ligand is known; it has a binding pocket of medium quality; it belongs to a druggable protein family. Antibody: a drug acting on it is in phase 2 or 3 trials; UniProt places it where antibodies can reach, with high confidence; its Gene Ontology location is reachable by antibodies, with high confidence; UniProt predicts a signal peptide or a membrane-spanning region. PROTAC: ubiquitination databases record sites on it; its protein half-life has been measured; a small molecule that binds it is known. Other modalities: an approved drug acts on it.
Target class: Secreted protein
Gene: Protein-coding gene on chromosome 19 (41,301,587 to 41,353,961, reverse strand). Ensembl gene ENSG00000105329.
Subcellular location: Secreted, extracellular space, extracellular matrix (Latency-associated peptide); Secreted (Transforming growth factor beta-1)
Subcellular location (Human Protein Atlas): Golgi apparatus; Plasma membrane; Basal body; Predicted to be secreted
Pathways (Reactome):
Disease: Influenza Virus Induced Apoptosis; SMAD2/3 Phosphorylation Motif Mutants in Cancer; TGFBR1 KD Mutants in Cancer; TGFBR1 LBD Mutants in Cancer; TGFBR2 Kinase Domain Mutants in Cancer; TGFBR2 MSI Frameshift Mutants in Cancer
Signal Transduction: Downregulation of TGF-beta receptor signaling; TGF-beta receptor signaling activates SMADs; TGF-beta receptor signaling in EMT (epithelial to mesenchymal transition); TGFBR3 regulates TGF-beta signaling
Extracellular matrix organization: ECM proteoglycans; Molecules associated with elastic fibres; Syndecan interactions
Gene expression (Transcription): RUNX3 regulates CDKN1A transcription; RUNX3 regulates p14-ARF; Regulation of RUNX3 expression and activity
Hemostasis: Cell surface interactions at the vascular wall; Platelet degranulation
Developmental Biology: Transcriptional regulation of white adipocyte differentiation
Immune System: Interleukin-4 and Interleukin-13 signaling
Metabolism of proteins: UCH proteinases
Gene Ontology:
Molecular function: cytokine activity; enzyme binding; growth factor activity; identical protein binding; protein binding; type I transforming growth factor beta receptor binding; type II transforming growth factor beta receptor binding; type III transforming growth factor beta receptor binding; protein serine/threonine kinase activator activity; protein-containing complex binding; transforming growth factor beta receptor binding
Biological process: aortic valve morphogenesis; ATP biosynthetic process; cell-cell junction organization; cellular response to hypoxia; cellular response to low-density lipoprotein particle stimulus; cellular response to transforming growth factor beta stimulus; chondrocyte differentiation; epithelial to mesenchymal transition; extracellular matrix assembly; extrinsic apoptotic signaling pathway; hematopoietic progenitor cell differentiation; hyaluronan catabolic process; membrane protein intracellular domain proteolysis; negative regulation of biomineral tissue development; negative regulation of blood vessel endothelial cell migration; negative regulation of cell cycle; negative regulation of cell differentiation; negative regulation of cell growth; negative regulation of cell population proliferation; negative regulation of cell-cell adhesion mediated by cadherin; negative regulation of DNA-templated transcription; negative regulation of epithelial cell proliferation; negative regulation of fat cell differentiation; negative regulation of gene expression; negative regulation of hyaluronan biosynthetic process; and 128 more
Cellular component: blood microparticle; cell surface; cytoplasm; extracellular matrix; extracellular region; microvillus; nucleus; Golgi lumen; plasma membrane; platelet alpha granule lumen; transforming growth factor beta complex; axon; neuronal cell body; secretory granule
Genetic constraint (gnomAD): Loss-of-function variants: 19 observed, 40.87 expected, observed/expected ratio (o/e) 0.46, 90% interval 0.32 to 0.68. The upper end of that interval is the gene's LOEUF score, 0.68, which puts it in group 2 of 6, group 1 being the genes least tolerant of losing a copy. Missense variants: 445 observed, 492.1 expected, observed/expected ratio (o/e) 0.9, 90% interval 0.84 to 0.98. Synonymous variants: 221 observed, 209.09 expected, observed/expected ratio (o/e) 1.06, 90% interval 0.95 to 1.18.
Gene-disease validity (ClinGen):
ClinGen rates the evidence that TGFB1 causes each of these diseases.
inflammatory bowel disease, immunodeficiency, and encephalopathy (autosomal recessive): Limited. An autosomal recessive disorder characterized by severe infantile inflammatory bowel disease manifesting as bloody diarrhea and failure to thrive, global developmental delay, epilepsy, brain atrophy and encephalopathy.
Homologues: Orthologues: chimpanzee TGFB1 (100% identical), macaque TGFB1 (99% identical), dog TGFB1 (95% identical), pig TGFB1 (95% identical), rat Tgfb1 (90% identical), mouse Tgfb1 (90% identical), guinea pig TGFB1 (87% identical), zebrafish tgfb1a (43% identical), zebrafish tgfb1b (42% identical). Paralogues in human: TGFB3 (47% identical), TGFB2 (46% identical), MSTN (23% identical), BMP6 (22% identical), BMP2 (22% identical), BMP4 (22% identical), GDF11 (22% identical), GDF6 (22% identical), BMP5 (21% identical), BMP10 (21% identical), BMP7 (21% identical), BMP8A (20% identical), and 19 more.
Diseases named in the same sentence as TGFB1 in open-access papers:
TGFB1 is named in the same sentence as 1,648 diseases in open-access papers, as found by Europe PMC text mining. Sharing a sentence is not in itself a finding about the gene and the disease. The quoted sentences say what the papers report.
breast cancer (2,867 papers, 1991 to 2026). A primary or metastatic malignant neoplasm involving the breast. "Our study identified serum levels of MIP-1b/CCL4, TGFβ1, and TGFβ2 were independently associated with breast cancer." (PMID 38541912, 2024). "High TGFB1 protein levels in tumor tissue were associated with poor prognosis in breast cancer patients, at least in some reports." (PMID 39468555, 2024). "The levels of TGFβ1 (≥46,713 pg/mL) and TGFβ2 (between 1005 and 2998 pg/mL) showed increasing O.R.s for breast cancer risk in LA only." (PMID 38541912, 2024). "We found that Groα/CXCL1 (obesity-associated), MIP-1b/CCL4 (obesity- and HTN-associated), TNFα (HTN-associated), and TGFβ1 and β2 (T2D-associated) were also significantly associated with breast cancer independently." (PMID 38541912, 2024). "Upregulated expression has resulted in poorly differentiated prostate cancer, high expression of TGFB1 is also associated with mammary epithelial and breast carcinoma, pancreatic cancer, colorectal cancer, lung cancer and metastatic melanoma." (PMID 39184376, 2024). "Primary human breast fibroblasts (HMF) stimulated with TGFβ1 have similar characteristics to breast cancer‐associated fibroblasts in vivo." (PMID 36534078, 2023). "Studies have identified the possible role of TGFβ-1+29C/T polymorphism in the pathogenesis of osteoarthritis, breast cancer, urinary bladder cancer, development of cervical lesions, sarcopenia, and chronic periodontitis." (PMID 36215278, 2022). "Another group studying TGFβ-1 +29 C/T polymorphism in breast cancer patients in India also identified TT to be a pathogenic genotype." (PMID 36215278, 2022). "TGFB1 also plays roles in tumour development and progression, and its increased expression is associated with an increased breast cancer risk." (PMID 33761981, 2021). "TGFB1 has a significant role in regulating macrophages in the mammary gland and impacts upon normal development and susceptibility to mammary cancer." (PMID 33761981, 2021). "The increased risk of breast cancer conferred by the presence of the TGFB1 L10P gene polymorphism suggests that increased production of TGFB1 is associated with increased susceptibility to breast cancer." (PMID 33761981, 2021). "The association of TGFB1 −509T with increased radiation-induced fibrosis was subsequently validated in a prospective cohort study following breast cancer patients over a minimum of 3 years after whole breast irradiation." (PMID 33202590, 2020). "In breast cancer patients, TGFB1 −509T and +869C alleles are associated with increased risk of fibrosis, while XRCC1 rs2682585 has been associated with decreased risk of fibrosis post radiation therapy." (PMID 33202590, 2020). "TGFBR2 and TGFB1 are considered putative targets of miR-21 that cause metastasis and patient poor prognosis in breast cancer." (PMID 28793339, 2017). "We searched the Oncomine database to determine any association between MDA-9 and TGFβ1 in breast cancer patient populations." (PMID 27863394, 2016). "We observed an association between the DNA copy numbers of MDA-9 and TGFβ1 in the breast cancer patient samples." (PMID 27863394, 2016). "It shows that highly aggressive basal-type breast cancer cell lines are characterized by both the high expressions of mesenchymal markers including TGFB1 and the markers associated with cancer stem-like features (CD44+/CD24−)." (PMID 26462028, 2015). "We further examined the involvement of TGFβ1 signaling on breast cancer risk using an ex vivo organoid culture model to assess stromal invasion." (PMID 25747469, 2015). "Treatment with both SID peptide and avermectins targets multiple key genes in the EMT pathway, including TGFB1, and it is noteworthy that inhibition of TGFβ activity has been associated with loss of KDM5B in basal-like breast cancer cells." (PMID 26460951, 2015). "In turn, breast cancer cells showed a significant enhanced spreading when plated on TGFβ1-treated, decorin-depleted, CAF-associated ECM." (PMID 25526025, 2014).
breast cancer (continued). "Nicoloso and colleagues investigated 38 previously identified breast cancer risk SNPs and found two to modify miRNA binding sites in TGFB1 and XRCC1 in vitro." (PMID 25390939, 2014). "The current evidence is consistent with a model in which the Pro-allele of TGFβ1 is hypermorphic and reduces the overall incidence of breast cancer." (PMID 23887657, 2013). "The proline-encoding (Pro-) allele of this SNP has been associated with an increased breast cancer risk, which has been attributed to the elevated secretion of this TGFβ1 variant observed in vitro and in male subjects." (PMID 23887657, 2013). "Here we investigated the association of the L10P SNP with serum levels of TGFβ1 in female breast cancer patients and controls." (PMID 23887657, 2013). "Except for TGFB1-rs1982073, all SNPs showed highly significant associations with breast cancer overall." (PMID 23544014, 2013). "The association of other TGFβ1 SNPs with breast cancer has also been analysed, such as the promoter SNPs C-509T and G-800A and the R25P coding SNP." (PMID 23887657, 2013). "Our results implicate TGFB1*29C genotype in modulating the risk for breast cancer in western Indian women." (PMID 21829601, 2011). "TGFB1 T29C gene polymorphism and risk for breast cancer in Maharashtrian subjects with respect to the age of onset." (PMID 21829601, 2011). "In breast cancer, overexpression of TGFβ1 was found to be associated with a higher occurrence of distant metastasis." (PMID 21063401, 2010). "This combined analysis revealed a highly significant three-fold increased risk of fibrosis following radiotherapy if a breast cancer patient carries at least one variant TGFβ1 (−509T) allele (P=0.00006) and this applies to over 50% of breast cancer patients." (PMID 17325707, 2007). "The authors observed that altered TGFB1 signaling levels altered breast cancer risk (intermediate vs. high signalers OR 1.27, 95% CI 0.93 – 1.74; low vs. high signalers OR 1.69, 95% CI 1.08 – 2.66)." (PMID 17848193, 2007). "More interesting is our observation that TGFB1 polymorphisms are inversely associated with ER+ breast cancers." (PMID 17848193, 2007). "Transforming growth factor-beta 1 (TGF-beta 1) is inhibitory for breast epithelial cells in vitro and treatment of breast cancer cell lines with tamoxifen results in a rise in TGF-beta 1 mRNA expression with associated inhibition of cell growth." (PMID 2021547, 1991). "The association of MIP-1b/CCL4, TGFβ1, and TGFβ2 and breast cancer were complicated." (PMID 38541912, 2024). "The effect was enhanced in the presence of conditioned medium from lymphatic endothelial cells that had been exposed to TGFβ1, suggesting that TGFβ1 induced the expression of genes in lymphatic endothelial cells that encode chemotactic factors for breast cancer cells with mesenchymal properties." (PMID 38055067, 2023). "Therefore, the results in TCGA cohort demonstrated that GZMA, GZMB, and IFNG in the low-risk group were highly expressed, while TGFB1 was elevated in high-risk breast cancer patients (p < 0.001)." (PMID 35619902, 2022). "The TGFB1 L10P gene is linked to the increased cellular expression of TGFB1, suggesting that increased abundance of TGFB1 might increase breast cancer risk." (PMID 33761981, 2021). "Given the role of TGFB1 in regulating macrophage phenotype and function, we proposed that TGFB-regulated macrophages could affect breast cancer susceptibility." (PMID 33761981, 2021). "The tumor suppressive functions are shown in murine studies of early tumorigenesis when constitutive expression of TGFB1 in the mammary gland results in decreased mammary tumor susceptibility when challenged with the chemical carcinogen 7,12-Dimethylbenz(a)anthracene (DMBA)." (PMID 34771552, 2021). "Further, expression of TGFB1 in breast cancers is associated with metastasis." (PMID 34771552, 2021).